NID2 (nidogen 2)
Diseases named in the same sentence as NID2 in open-access papers (continued):
Sharing a sentence is not in itself a finding about the gene and the disease.
glioma (1 paper, 2025). A benign or malignant brain and spinal cord tumor that arises from glial cells (astrocytes, oligodendrocytes, ependymal cells). "The present study investigated the prognostic value of NID2 in glioma and its associated molecular pathways and functional roles in malignant progression." (PMID 40332526, 2025). "Kaplan–Meier survival curves showed that NID2 high expression was associated with significantly worse overall survival (OS) for all glioma patients (p < 0.0001)." (PMID 40332526, 2025). "RNA-Seq was performed to study transcriptomic changes associated with NID2 overexpression in glioma cells." (PMID 40332526, 2025). "Our study suggests that the characterization of an immunoreactivity score using NID2 IHC on pathology specimens provides a potential method for assessing glioma aggressiveness." (PMID 40332526, 2025). "It is of great interest to conduct studies assessing serum and cerebrospinal fluid (CSF) NID2 levels as predictive cancer markers during the clinical workup of glioma patients." (PMID 40332526, 2025). "To explore molecular pathways activated by the upregulation of NID2 in glioma cells, we created two stable NID2-overexpressing cell lines using U87MG and T98G cells." (PMID 40332526, 2025). "To understand the molecular pathways of NID2 overexpression in glioma progression, we created two stable cell lines that overexpress NID2." (PMID 40332526, 2025). "Results from in vitro assays supported the gene pathway activation data that NID2 overexpression promoted glioma cell proliferation, migration, and invasion." (PMID 40332526, 2025). "The performed analyses included investigating the NID2 expression profile using the Cancer Genome Atlas (TCGA), Chinese Glioma Genome Atlas (CGGA), and tumor tissue microarray." (PMID 40332526, 2025). "In grade 4 glioma, there was diffuse cytoplasmic staining of NID2, consistent with its upregulation in glioma cells." (PMID 40332526, 2025). "Our current study is the first to show that NID2 overexpression in glioma is correlated with higher tumor grade and poor patient survival." (PMID 40332526, 2025). "Our experiments using NID2-overexpressing glioma cell lines confirmed that NID2 overexpression leads to more robust proliferation, migration, invasion, and anti-apoptosis activities." (PMID 40332526, 2025). "The activation results of the GSEA pathways were confirmed by Western blotting analysis, where p-Akt and Bcl-xL were upregulated in the NID2-overexpressing glioma cells." (PMID 40332526, 2025). "A TMA with 120 glioma samples was analyzed and showed high NID2 protein expression levels were correlated with GBM status." (PMID 40332526, 2025). "The volcano plots presented the expression of 275 DEGs in glioma, and NID2 expression was shown to have high expression in glioma compared with the controls." (PMID 40332526, 2025). "In stably NID2-overexpressed glioma cells, RNA-Seq analysis revealed coactivation of oncogenic functional pathways, including cell proliferation, survival, epithelial–mesenchymal transition, ECM organization, and migration." (PMID 40332526, 2025). "Thus, we can further improve glioma patient prognosis by adding NID2 expression to the current known list of molecular prognostic markers." (PMID 40332526, 2025). "Our results show that NID2 is a promising prognostic marker in glioma." (PMID 40332526, 2025). "We used GTEx as the normal brain control and showed significant NID2 overexpression in glioma." (PMID 40332526, 2025). "In addition, the ECM of grade 4 glioma showed immunoreactivity for NID2, consistent with its function as a secreted protein." (PMID 40332526, 2025). "A transwell invasion assay was performed to test whether NID2 overexpression influences the invasive ability of glioma cells." (PMID 40332526, 2025). "Our current study shows that high expression of NID2 in glioma is an adverse prognostic factor." (PMID 40332526, 2025).
glioma (continued). "Previous studies have shown that NID2 is deregulated in several types of cancer, but its role in glioma is unknown." (PMID 40332526, 2025). "We analyzed the expression levels of NID2 in the TCGA glioma dataset." (PMID 40332526, 2025). "Our immunohistochemistry study of NID2 in TMA confirmed the bioinformatic findings and pointed to the possibility of using NID2 IHC in the identification of higher-grade glioma in the practice of pathology diagnosis." (PMID 40332526, 2025). "Furthermore, GSEA analysis suggested that processes such as apoptosis genes were negatively regulated with NID2 overexpression and PI3K-Akt signaling pathway genes were activated by NID2 overexpression in glioma cells." (PMID 40332526, 2025). "This study aimed to investigate the predictive value of NID2 by analyzing the glioma clinical datasets, including GSE16011, GSE7696, GSE4290, the Cancer Genome Atlas (TCGA), the Chinese Glioma Genome Atlas (CGGA), and a glioma tissue microarray (TMA)." (PMID 40332526, 2025). "Here, we demonstrated that NID2 overexpression was an additional independent adverse prognostic factor for all gliomas, and it had an additive negative prognostic effect in addition to IDH mutation and 1p/19q codeletion status analyses for patient survival." (PMID 40332526, 2025).
Hepatic fibrosis (1 paper, 2024). The presence of excessive fibrous connective tissue in the liver. "These histological analyses demonstrated an increased frequency/size lipid droplets, enhanced lipid deposition, and higher hepatic fibrosis in male NID2-AAV-injected mice, in contrast with sex-matched controls." (PMID 39684493, 2024). "Additionally, in male mice, overexpression of NID2 increased liver fibrosis, which is a key determinant of the progression of simple steatosis to NASH." (PMID 39684493, 2024).
Hepatic steatosis (1 paper, 2024). Steatosis is a term used to denote lipid accumulation within hepatocytes. "Since (a) NID2 expression is elevated in steatotic livers of HFD-fed mice, and (b) NID2 overexpression increases liver weight in male mice, we investigated the role of NID2 in regulating hepatic steatosis and fibrosis." (PMID 39684493, 2024). "Our data demonstrate that NID2 overexpression in male mice promotes hepatic steatosis, as evidenced by increased triglyceride, NEFA levels, and ORO staining of liver frozen sections, as well as increased plasma triglycerides." (PMID 39684493, 2024).
Landau-Kleffner syndrome (1 paper, 2022). A rare form of epileptic encephalopathy with spike-wave activation in sleep (EE-SWAS) characterized by various combinations of acquired cognitive, language, behavioral, and motor deficits associated with marked spike- and- wave activation in sleep. "For instance, NID2, which has been associated in humans with the Landau-Kleffner syndrome, a rare language disorder with suspicions of hearing loss." (PMID 35580588, 2022).
metastatic cancer (1 paper, 2016). A carcinoma which has spread from the original site of growth to another anatomic site. "In this study, the functional role of NID2 in the suppression of in vivo metastasis was examined by intrasplenic injection of metastatic cancer cells." (PMID 27793011, 2016).
metastatic disease (1 paper, 2024). "Our data show that the future development of an NID2-targeting approach offers an attractive option to not only reduce primary tumor growth but also impede liver metastasis in this highly aggressive and metastatic disease." (PMID 38959305, 2024).
microphthalmia (1 paper, 2024). Congenital or developmental anomaly in which the eyeballs are abnormally small. "This study is the first to map the expression patterns of NID2, LUM, and COL4A1 in stem cell-derived OVs and show their association in microphthalmia." (PMID 38821055, 2024). "The upregulation of LUM and other ECM proteins such as NID2 and COL4A1 in microphthalmia patient OVs in contrast to the loss of Lumican in animal models of increased axial length may be indicative of an inversely proportional relationship between the ECM and axial length." (PMID 38821055, 2024). "The overproduction of ECM components, including LUM, NID2, and COL4A1 that encapsulate and infiltrate the OV, may potentially physically limit ocular growth and development, resulting in eye malformations such as microphthalmia." (PMID 38821055, 2024).
osteoarthritis (1 paper, 2025). A noninflammatory degenerative joint disease occurring chiefly in older persons, characterized by degeneration of the articular cartilage, hypertrophy of bone at the margins and changes in the synovial membrane. "Higher levels of GREM1 and S100A6, however, correlate with osteoarthritis, opposing the expression of NID2 and EDIL3." (PMID 40224957, 2025). "NID2 and EDIL3 are more frequently associated with cartilage than tendon, but both protect chondrocytes against osteoarthritis." (PMID 40224957, 2025).
pancreatic cancer (1 paper, 2024). "High NID2 expression is associated with several malignancies, but its role in pancreatic cancer progression and metastasis had been relatively unexplored." (PMID 38959305, 2024). "In pancreatic cancer, we now show that high NID2 expression is associated with poor patient survival, particularly for basal-like tumors, via analysis of the ICGC PDAC cohort." (PMID 38959305, 2024). "Here, we demonstrate that NID2 is associated with poor patient outcomes in pancreatic cancer and that it is predominantly expressed by stromal cells such as CAFs." (PMID 38959305, 2024). "Patients with basal-like tumors have worse outcomes compared to classical tumors, indicating that high NID2 is associated with the most aggressive pancreatic cancer cases." (PMID 38959305, 2024). "We reveal that reducing NID2 impaired metastasis and improved response to chemotherapy in orthotopic models of pancreatic cancer, revealing NID2 as a potential cotarget in this deadly disease." (PMID 38959305, 2024). "Overall, these data demonstrate that reducing NID2 in the stromal compartment can alter matrix organization, resulting in an impairment in pancreatic cancer invasion in 3D organotypic settings." (PMID 38959305, 2024). "Our exploration of NID2 biology in pancreatic cancer was conducted using standard-of-care gemcitabine/Abraxane chemotherapy with immunocompromised mouse models." (PMID 38959305, 2024). "Collectively, using tissue decellularization coupled with temporally resolved MS proteomics, we reveal NID2 as a promising cotarget with a potential dual role in pancreatic cancer." (PMID 38959305, 2024). "Overall, these orthotopic experiments demonstrate the role NID2 plays in facilitating pancreatic cancer metastasis." (PMID 38959305, 2024). "Using CRISPRi technology, we knocked down the expression of NID2 in CAFs to assess its functional role in pancreatic cancer." (PMID 38959305, 2024). "Considering the clinical data linking high NID2 expression with poor pancreatic cancer patient outcomes, we aimed to assess the functional role of NID2 using cancer cells and CAFs derived from the KPC mouse model." (PMID 38959305, 2024). "This approach allowed us to dissect the fibrotic signatures of pancreatic tumors to find matrisomal cotargets such as NID2 in PDAC." (PMID 38959305, 2024). "Using intravital imaging, we show that NID2 targeting increases vascular coverage and promotes the formation of more patent vessel networks in live pancreatic tumors under chemotherapy treatment." (PMID 38959305, 2024). "Future work could include investigating the reciprocal signaling between pancreatic cancer cells and fibroblasts, which occurs to drive increased stromal NID2 expression." (PMID 38959305, 2024). "In addition, it is not well understood which signaling pathways regulate increased NID2 expression in the context of pancreatic cancer." (PMID 38959305, 2024). "Considering the known aberrations in axonal guidance genes within metastatic pancreatic cancer, future work could involve an assessment in the NID2-depleted setting for these pathways." (PMID 38959305, 2024). "Considering this, we decided to further investigate the role of NID2 in pancreatic cancer." (PMID 38959305, 2024). "Hence, we investigated how NID2 can promote pancreatic cancer invasion and metastasis." (PMID 38959305, 2024). "Furthermore, Kaplan-Meier analysis of NID2 mRNA expression and patient survival in the International Cancer Genome Consortium (ICGC) PDAC cohort (n = 267) reveals that high NID2 expression is associated with poorer overall survival in patients with pancreatic cancer." (PMID 38959305, 2024).
thyroid cancer (1 paper, 2024). "Notably, these candidate IFT57-dependent genes have reported functions in other cancers, and roles for GAS6 and NID2 have been reported in thyroid cancer." (PMID 39201643, 2024).
tubulointerstitial nephritis (1 paper, 2012). "Other proteins detected included collagen VI α-1/α-2 (Col6a1/Col6a2), fibrinogen beta chain (FGB), transglutaminase 2 isoform A (TGM2A), b-actin variant (ACTB), 70 kD heat shock protein 5 (HSPA5), nidogen 2 (NID2), CD49f, βIG-H3, and tubulointerstitial nephritis (TIN)." (PMID 22701492, 2012).
urothelial carcinoma (1 paper, 2020). A malignant neoplasm derived from the transitional epithelium of the urinary tract (urinary bladder, ureter, urethra, or renal pelvis). "Abern studied the role of two methylated genes, TWIST1 and NID2 based on Renard work due to their high sensitivity and specificity for urothelial carcinoma." (PMID 32664878, 2020).
cancer (27 papers, 2007 to 2025). A tumor composed of atypical neoplastic, often pleomorphic cells that invade other tissues. "NID2 expression has been linked to the development of various cancers, including ovarian, lung, gastric, pancreatic, and oral squamous cell carcinoma." (PMID 39684493, 2024). "Previous studies demonstrated that NID2 was significantly overexpressed in many cancer tissues and positively associated with TNM stage." (PMID 36106120, 2022). "The NID2 gene encodes one of the basic components of the basement membrane and plays a key role in embryogenesis and the development of malignant tumors." (PMID 35216235, 2022). "Among those genes, we found up-regulation of αSma/Acta2, a marker of activated and cancer-associated fibroblasts, and Nidogen-2, Lamb2, and Prelp, which encode for ECM-associated proteins." (PMID 29725010, 2018). "Down-regulation of the nidogens (NID1 and NID2) de-stabilizes the basement membrane and has been associated with cancer formation." (PMID 25093596, 2014). "Consequently, loss of NID-2 has been implicated in various malignant neoplasms, such as gastric and lung carcinomas." (PMID 38550383, 2024). "Several studies reveal Nidogen-Laminin interactions as basis for the important role for Nidogen-2 (NID-2) during cancer metastasis and NID-2 has been recently identified as a suitable biomarker for cancer progression." (PMID 38550383, 2024). "Here, we used intravital imaging to assess tumor characteristics in live subcutaneous tumors consisting of either control CAFs or NID2-depleted CAFs coinjected with eGFP-tagged cancer cells." (PMID 38959305, 2024). "These 3D organotypic matrix invasion assays revealed a reduction in the ability of the KPC cancer cells to invade into NID2 knockdown organotypic matrices compared to control." (PMID 38959305, 2024). "Our assessment at early-, mid-, and late-stage disease reveals an increased abundance of nidogen-2 (NID2) in the KPC model compared to KPflC, with further validation showing that NID2 is primarily expressed by cancer-associated fibroblasts (CAFs)." (PMID 38959305, 2024). "Collectively, we show that depleting NID2 results in biochemical and biomechanical alterations, which also impairs subsequent cancer cell invasion in 3D organotypic models." (PMID 38959305, 2024). "We show that NID2 reduction regulates matrix deposition and biomechanics in three-dimensional (3D) organotypic models, leading to decreased cancer cell invasion." (PMID 38959305, 2024). "NID2 suppresses the EGFR/Akt and integrin/focal adhesion kinase (FAK)/PLC metastasis-related pathways; these data shed light on NID2’s critical tumor metastasis-suppression functions in cancer." (PMID 34976811, 2021). "Researches on the NID2 methylation status and its dysfunction, which results in cancer, have been consistently published, increasing the reliability and importance of NID2." (PMID 32171289, 2020). "Although NID2 methylation is a promising marker for cancer screening, a larger sample size is necessary, and a different cohort should be used for unequivocal results." (PMID 32171289, 2020). "Via both bioinformatic analysis and in vitro investigation, we confirmed the methylation of NID2 related to cancer in cases of OSCC." (PMID 32171289, 2020). "Collectively, this suggests that at cg22881914 of NID2, the methylation had transition when normal epithelial cell completely transform to cancer cells." (PMID 32171289, 2020). "Recently, the reduction in the NID2 mRNA and protein level has been determined in cancer tissue samples as well as in nude mice xenograft model." (PMID 32171289, 2020). "The relationship between NID2 hypermethylation and cancer had been reported in terms of downregulation of NID2 expression in several cancers, suggesting tumor-suppressor activity of NID2." (PMID 32171289, 2020).